N4BP2L2 (NEDD4 binding protein 2 like 2)
Synonyms: CG005; PFAAP5; 92M18.3; CG016
Tractability: PROTAC: ubiquitination databases record sites on it.
Gene: Protein-coding gene on chromosome 13 (32,432,417 to 32,538,885, reverse strand). Ensembl gene ENSG00000244754.
Subcellular location (Human Protein Atlas): Nucleoplasm
Gene Ontology:
Molecular function: enzyme binding; protein binding; transcription corepressor activity
Biological process: negative regulation of hematopoietic stem cell differentiation; positive regulation of hematopoietic stem cell proliferation; negative regulation of transcription by RNA polymerase II
Cellular component: extracellular exosome; nucleus; transcription repressor complex
Genetic constraint (gnomAD): Loss-of-function variants: 40 observed, 47.15 expected, observed/expected ratio (o/e) 0.85, 90% interval 0.66 to 1.1. The upper end of that interval is the gene's LOEUF score, 1.1, which puts it in group 4 of 6, group 1 being the genes least tolerant of losing a copy. Missense variants: 638 observed, 661.9 expected, observed/expected ratio (o/e) 0.96, 90% interval 0.9 to 1.03. Synonymous variants: 186 observed, 218.67 expected, observed/expected ratio (o/e) 0.85, 90% interval 0.75 to 0.96.
Homologues: Orthologues: macaque N4BP2L2 (93% identical), dog N4BP2L2 (74% identical), rat N4bp2l2 (65% identical), mouse N4bp2l2 (63% identical), tropical clawed frog n4bp2l2 (30% identical), zebrafish n4bp2l2 (24% identical), chimpanzee N4BP2L2 (20% identical). Paralogues in human: N4BP2 (21% identical), N4BP2L1 (15% identical).
Diseases named in the same sentence as N4BP2L2 in open-access papers:
N4BP2L2 is named in the same sentence as 12 diseases in open-access papers, as found by Europe PMC text mining. Sharing a sentence is not in itself a finding about the gene and the disease. The quoted sentences say what the papers report.
breast carcinoma (2 papers, 2018 to 2025). "Together with Random Forest analysis and validation in an independent breast cancer cohort, these results identify N4BP2L2 as a robust suppressor of EXO1-induced HR deficiency." (PMID 41323735, 2025).
epithelial ovarian cancer (2 papers, 2020). "Both BRCA2 and STARD13 are well known tumor-suppressors, and upregulation of N4BP2L1 and N4BP2L2 has been associated with positive prognosis in ovarian cancer cases." (PMID 32404140, 2020). "For example, circRNAs EXOC6B and N4BP2L2 can be used as prognostic biomarkers for epithelial ovarian cancer, and circ_0081001 is a potential marker for the diagnosis of osteosarcoma." (PMID 32378344, 2020).
colorectal cancer (1 paper, 2022). A primary or metastatic malignant neoplasm that affects the colon or rectum. "Circ-3823, circ-IL4R, and circ-N4BP2L2 were significantly overexpressed in colorectal cancer cells, which indicates a poor prognosis in colorectal cancer patients." (PMID 36291546, 2022).
coronary artery disease (1 paper, 2024). "N4BP2L2 also appears to be associated with the risk of coronary artery disease." (PMID 38674024, 2024).
uveitis (1 paper, 2025). An inflammatory process affecting a part of or the entire uvea. "For instance, in the uveitis only group, the genes KLHL21, MYLIP, ZNFX1, PDE4A, TNFRSF21, and N4BP2L2 were downregulated, while METTL72, GAPT, CD180, CCR2, and TLR7 were upregulated when comparing uveitis patients with healthy controls." (PMID 40270958, 2025).
cancer (1 paper, 2020). A tumor composed of atypical neoplastic, often pleomorphic cells that invade other tissues. "Other genes from this list are linked to various types of cancer (Pnck, Calu, Vav2, Kif3a, Adgrf5, N4bp2l2)." (PMID 32467583, 2020).
N4BP2L2 also shares sentences with these, for which no sentence is quoted: tumor (2 papers); cholangiocarcinoma (1); non-small cell lung carcinoma (1); osteosarcoma (1); ovarian cancer (1); pediatric acute myeloid leukemia (1).